MAGED4 (MAGE family member D4)
Description:
May enhance ubiquitin ligase activity of RING-type zinc finger-containing E3 ubiquitin-protein ligases. Proposed to act through recruitment and/or stabilization of the Ubl-conjugating enzyme (E2) at the E3:substrate complex.
Synonyms: KIAA1859; MAGE1; MGC3210; MAGE-E1; MAGE-D4
Tractability: PROTAC: ubiquitination databases record sites on it.
Gene: Protein-coding gene on chromosome X (52,184,767 to 52,192,268, forward strand). Ensembl gene ENSG00000154545.
Gene Ontology:
Molecular function: protein binding
Biological process: negative regulation of transcription by RNA polymerase II
Cellular component: nucleus
Homologues: Orthologues: chimpanzee MAGED4 (99% identical), macaque MAGED1 (98% identical), zebrafish ndnl2 (13% identical), Drosophila melanogaster MAGE (8% identical). Paralogues in human: MAGED4B (100% identical), MAGED1 (43% identical), TRO (35% identical), MAGED2 (30% identical), MAGEL2 (22% identical), MAGEE1 (18% identical), MAGEB4 (17% identical), MAGEB17 (17% identical), MAGEB18 (16% identical), MAGEB1 (16% identical), MAGEB10 (16% identical), MAGEB2 (16% identical), and 25 more.
Diseases named in the same sentence as MAGED4 in open-access papers:
MAGED4 is named in the same sentence as 17 diseases in open-access papers, as found by Europe PMC text mining. Sharing a sentence is not in itself a finding about the gene and the disease. The quoted sentences say what the papers report.
glioma (5 papers, 2019 to 2025). A benign or malignant brain and spinal cord tumor that arises from glial cells (astrocytes, oligodendrocytes, ependymal cells). "The association of MAGED4 overexpression with poor prognosis of glioma patients has been previously reported." (PMID 33425727, 2020). "DNA hypomethylation associated overexpression of MAGED4 has previously been reported in glioma." (PMID 33425727, 2020). "In view of the reported overexpression of MAGED4 in glioma, we focused our further analysis on downregulated T2Ms using MAGEH1 as a representative member of this highly co-expressed T2M subgroup." (PMID 33425727, 2020). "Although contradictory reports also exist regarding maternal imprinting of the Necdin gene, epigenetic regulation of MAGED4 in glioma is documented." (PMID 33425727, 2020). "Since the MAGED4 promoter contains a CpG island, we confirmed, via in vitro promoter methylation and luciferase reporter assays, that promoter methylation suppresses MAGED4 transcriptional activity, consistent with our prior findings in glioma." (PMID 41465204, 2025). "However, significant intratumoral heterogeneity of MAGED4 expression has been observed in tumors such as glioma and colon cancer." (PMID 41465204, 2025). "METTL7B and MAGED4 were discovered to be overexpressed prognostic markers in various gliomas." (PMID 36900348, 2023). "In agreement to this, our analysis revealed that while MAGED1, which is co-expressed with MAGED4, was associated with poor prognosis in glioma, it did not emerge as an independent prognostic factor in multivariate analysis." (PMID 33425727, 2020). "In gliomas, AZA upregulates CTAs, including melanoma-associated antigen D4 (MAGED4)." (PMID 31652645, 2019). "While DNA methylation is known to regulate MAGED4 expression in glioma, no information about its role in regulating the expression of other T2M genes is available." (PMID 33425727, 2020). "Interestingly, Oncomine analysis revealed that in glioma, several MAGE genes, including MAGED1, MAGED4, and MAGED4B exhibited elevated expression." (PMID 33425727, 2020).
oral squamous cell carcinoma (2 papers, 2022 to 2025). "Melanoma-associated antigen D4 (MAGED4) has been proposed as a potential immunotherapeutic target in oral squamous cell carcinoma (OSCC)." (PMID 41465204, 2025).
head and neck cancer (1 paper, 2025). A primary or metastatic malignant neoplasm affecting the head and neck. "This vaccine exhibited enhanced immunogenicity and synergistic anti-tumor effects in head and neck cancer patients, providing strong experimental evidence for targeting MAGED4 in OSCC immunotherapy." (PMID 41465204, 2025).
mesothelioma (1 paper, 2025). A usually malignant and aggressive neoplasm of the mesothelium which is often associated with exposure to asbestos. "The proteins that were unique to mesothelioma samples (cell line and PE samples) were MAGED4, PRAME, WT1, ACRBP, EPHA2 and SOX11." (PMID 39921204, 2025).
tumor (6 papers, 2008 to 2025). "The overexpression of MAGED4 has been associated with enhanced tumor cell proliferation, migration and poorer patient prognosis." (PMID 41465204, 2025). "Building on these efforts, combining epigenetic drugs with MAGED4-targeted immunotherapy is expected to overcome heterogeneity and enhance anti-tumor activity." (PMID 41465204, 2025). "Analysis of the Oncomine OSCC dataset (n = 62) revealed a significant increase of MAGED4 mRNA expression in tumor tissues compared to normal controls (p < 0.001)." (PMID 41465204, 2025). "In contrast to other members of the MAGE family, MAGED4 demonstrates low expression levels in many tumor tissues, while its expression in NSCLC is relatively high and significantly higher in SqCLC than in adenocarcinoma." (PMID 38398111, 2024). "However, a borderline correlation was observed for progression-free interval (PFI) with a p-value of 0.05, suggesting a possible role of MAGED4 in tumor progression." (PMID 41465204, 2025). "E-protein promotes MAGED4 and MAGED4B (melanoma antigen family members) which have tumor antigenic properties and elicit T-cell responses against tumor/tissue cells." (PMID 35723340, 2022). "After confirming MAGED4 overexpression in bulk OSCC tissues at both mRNA and protein levels, we next analyzed its expression patterns at the single-cell level resolution within the tumor microenvironment." (PMID 41465204, 2025). "In addition to its expression in tumor cells within OSCC tissues, MAGED4 is also detected in some of the endothelial cells and fibroblasts." (PMID 41465204, 2025). "Such differential antigen distribution may cause a “partial antigen exposure and partial immune escape” phenomenon: tumor cells with low/negative MAGED4 expression evade immune recognition, while only MAGED4-positive subpopulations are targeted." (PMID 41465204, 2025). "Although single-cell sequencing shows heterogeneous MAGED4 expression across different cell types in tumors, we used OSCC cell lines to evaluate drug-induced MAGED4 expression, as tumor cells are the most abundant component of tumor tissue and the primary target of anti-tumor immunity." (PMID 41465204, 2025).
cancer (5 papers, 2015 to 2025). A tumor composed of atypical neoplastic, often pleomorphic cells that invade other tissues. "Top presented HLA class I TAP-U source genes KIF2C, MAGED4, and EGFR have shown immunogenicity in cancer context." (PMID 39136024, 2024).
MAGED4 also shares sentences with these, for which no sentence is quoted: adenocarcinoma (1 paper); colorectal carcinoma (1); esophageal cancer (1); esophageal squamous cell carcinoma (1); hepatocellular carcinoma (1); lung carcinoma (1); lymph node metastasis (1); melanoma (1); non-small cell lung carcinoma (1); oral cancer (1); renal cell carcinoma (1).